NRGN (neurogranin)
Diseases named in the same sentence as NRGN in open-access papers (continued):
Sharing a sentence is not in itself a finding about the gene and the disease.
mild cognitive impairment (33 papers, 2015 to 2026). "The altered expression of NRGN leads to loss of synaptic plasticity and schizophrenia-associated cognitive deficits." (PMID 35958988, 2022). "Also, studies revealed SNAP25 delivers significant association of the neurogranin and cognitive impairment from PD patients." (PMID 41327336, 2025). "Our findings are consistent with prior studies showing higher SNAP-25, synaptotagmin-1, GAP-43, and neurogranin levels in CSF are associated with cognitive impairment in AD, which may be linked to synapse degeneration in the brain." (PMID 38299587, 2024). "High baseline cerebrospinal fluid neurogranin levels in a mild cognitive impairment group were correlated with longitudinal reductions in cortical glucose metabolism and hippocampal volume at clinical follow-up." (PMID 33212853, 2020). "The levels of neurogranin in CSF of AD or mild cognitive impairment (MCI) patients were higher than in cognitively-normal elderly patients." (PMID 30965555, 2019). "Significant associations were observed between increased concentration of neurogranin and cognitive impairment in total Parkinson’s disease group (p = 0.017), as well as in the drug naïve (p = 0.021) and with motor disease stage (p = 0.041)." (PMID 28649607, 2017). "It is believed that the hypofunction of neurogranin may lead to experience-dependent developmental deficits in excitatory synapse connectivity or cognitive impairment, thereby potentially contributing to the pathogenesis of psychosis." (PMID 38671846, 2024). "Furthermore, increased concentrations of neurogranin in CSF predict cognitive decline from mild cognitive impairment (MCI) to AD." (PMID 36045450, 2022). "Similarly, elevated baseline CSF neurogranin levels in patients with mild cognitive impairment forecasted a decline in cognition and corroborated significant longitudinal reductions of hippocampal volume at clinical follow-up." (PMID 33578866, 2021). "Increased concentrations of Neurofilament Light Polypeptide (NLP) and neurogranin in the CSF and blood correlates with the degree of cognitive impairment and may be useful in the prognosis of the development of cognitive disorders in AD." (PMID 33671562, 2021). "Another recent study focusing on cognitively normal (CN) individuals has found that elevated levels of CSF NFL but not CSF tTau, pTau or neurogranin (Ng) were a risk factor for mild cognitive impairment (MCI)." (PMID 31514172, 2019). "For example, low levels of neurogranin show a clear correlation with cognitive deficits and aging." (PMID 26555887, 2015). "A recent Chinese study revealed that exosomal SNAP25, GAP43, neurogranin, and synaptotagmin-1, combined with APOE ε4 status, improved diagnostic accuracy (AUC = 0.88), acting as a useful biomarkers panel for the prediction of AD five to seven years before cognitive impairment." (PMID 35360215, 2022). "Moreover, we found significantly lower CSF SNAP-25 (p = 0.025), β-synuclein (p = 0.044), and neurogranin (p = 0.007) levels in PwMS with vs. without domain-specific cognitive impairment." (PMID 39708160, 2024). "CSF samples from 95 individuals including 39 patients with AD dementia (AD-D), 13 with mild cognitive impairment (MCI) due to AD (MCI-AD), 29 with MCI not due to AD (MCI-o) and 14 patients with non-AD dementias (non-AD-D) were analyzed for neurogranin and YKL-40." (PMID 26698298, 2015).
schizophrenia (30 papers, 2012 to 2026). A major psychotic disorder characterized by abnormalities in the perception or expression of reality. "miR-137 regulates key schizophrenia-associated genes, including NRGN and CACNA1C, affecting neural development and function." (PMID 40779062, 2026). "Neurogranin (NRGN) is a calmodulin-binding protein, and it has been associated with Alzheimer’s disease and schizophrenia." (PMID 35073995, 2022). "A genome‐wide association study identified a significant association with schizophrenia at a locus near the NRGN gene in European populations." (PMID 33270377, 2021). "A genome-wide association study identified a relationship between schizophrenia and the single nucleotide polymorphism of rs12807809 in the NRGN." (PMID 33132903, 2020). "In another example, we captured a ∼4 kb haplotype block containing a GWAS SNP associated with schizophrenia (rs12807809), located immediately upstream of the NRGN gene on chromosome 11." (PMID 31031799, 2019). "Based on genome-wide association studies, a single-nucleotide polymorphism in the NRGN gene (rs12807809) is considered associated with schizophrenia (SZ)." (PMID 30953482, 2019). "NRGN is a schizophrenia risk gene and fragile-X mental retardation protein (FMRP) target that is involved in memory formation." (PMID 31819040, 2019). "Previous study have found that the association between several SNPs in ZNF804A, NRGN and schizophrenia were different across distinct ethic population, the significance level in Asian populations were not across the whole genome." (PMID 29599495, 2018). "In the present study we used multimodal brain imaging to explore potential effects of the schizophrenia risk gene NRGN on two independent schizophrenia-related brain-based intermediate phenotypes in schizophrenia patients and healthy controls." (PMID 24098564, 2013). "Our study highlights the effects of schizophrenia risk variants in the NRGN gene on functional and structural brain-based intermediate phenotypes for schizophrenia." (PMID 24098564, 2013). "Taken together, our study highlights the effects of schizophrenia risk variants in the NRGN gene on brain-based intermediate phenotypes for schizophrenia – DLPFC inefficiency during a working memory task and reduced cortical thickness." (PMID 24098564, 2013). "A recent study of more than 300,000 single nucleotide polymorphisms (SNPs) in 12,945 schizophrenia patients and 34,591 healthy controls reported associations at genome-wide significance with rs12807809 located near neurogranin (NRGN)." (PMID 24098564, 2013). "Here, we studied the effects of NRGN risk variants on brain-based intermediate phenotypes for schizophrenia." (PMID 24098564, 2013). "We have found that the genome-wide supported variant of the NRGN gene is associated with the brain morphology of the anterior cingulate cortex in patients with schizophrenia." (PMID 24160291, 2013). "Because rostral ACC volume reduction, especially in the left hemisphere, has been associated with both, a diagnosis of schizophrenia and NRGN risk variants, we also investigated NRGN genotype effects on left rostral ACC volume in an additional analysis." (PMID 24098564, 2013). "New schizophrenia risk genes discovered through genome-wide association studies (GWAS), such as neurogranin (NRGN), can be used to identify these mechanisms." (PMID 24098564, 2013). "Two schizophrenia-associated NRGN SNPs (rs12807809 and rs12541) were tested for association with working memory-elicited dorsolateral prefrontal cortex (DLPFC) activity and surface-wide cortical thickness." (PMID 24098564, 2013). "Further research will be required to clarify the function of the risk NRGN variant on the pathophysiology of schizophrenia." (PMID 22253779, 2012). "Five genes (SELL, HLA-DRB1, CEBPD, HSPA5, and NRGN) from the matched list had been previously studied for schizophrenia with positive association signals, the rest of the genes were involved in immune responses or other neuronal diseases." (PMID 23282246, 2012).
schizophrenia (continued). "This is the first study to identify brain morphology associated with genome-wide significant risk variants in NRGN for schizophrenia at the whole brain level." (PMID 22253779, 2012). "The rs12807809 single-nucleotide polymorphism in NRGN is a genetic risk variant with genome-wide significance for schizophrenia." (PMID 22253779, 2012). "In this study, we examined the impacts of the NRGN polymorphism and the genotype-diagnosis interaction on GM volumes and WM volumes in patients with schizophrenia and in healthy volunteers." (PMID 22253779, 2012). "Third, the associations between NRGN and both brain function and cortical thickness in schizophrenia patients may be influenced by the effects of antipsychotic medications." (PMID 24098564, 2013). "Furthermore, NRGN has been implicated in neuronal cortico- and synaptogenesis during brain development – both found to be impaired in schizophrenia." (PMID 24098564, 2013). "Our findings suggest that the genome-wide associated genetic risk variant in the NRGN gene may be related to a small GM volume in the ACC in the left hemisphere in patients with schizophrenia." (PMID 22253779, 2012). "Altered NRGN activity may therefore mediate the effects of the NMDA hypofunction implicated in the pathophysiology of schizophrenia." (PMID 22253779, 2012). "In conclusion, we found that a genome-wide supported variant of NRGN may be associated with brain morphological vulnerability of the left ACC in patients with schizophrenia." (PMID 22253779, 2012). "Neurogranin has been implicated in neurodevelopmental disorders such as ADHD, autism, and schizophrenia and is a postsynaptic protein kinase that binds to calmodulin in the absence of calcium." (PMID 41386992, 2026). "NRGN was one of the first GWAS schizophrenia hits, and has been shown to be downregulated in brain tissue of schizophrenics." (PMID 31113746, 2019). "Our results revealed the influence of the NRGN gene on thalamocortical morphology in schizophrenia involving widespread cortical thinning and thalamic shape abnormalities." (PMID 24386483, 2013). "Although the genome wide supported psychosis susceptibility neurogranin (NRGN) gene is expressed in human brains, it is unclear how it impacts brain morphology in schizophrenia." (PMID 24386483, 2013). "To date, GWASs on schizophrenia have identified several genome-wide significant associated variants located in the zinc finger protein 804A (ZNF804A), neurogranin (NRGN), transcription factor 4 (TCF4) genes and a major histocompatibility complex (MHC) region." (PMID 24160291, 2013). "There is evidence from one earlier study of reductions of NRGN proteins in prefrontal cortex of patients with schizophrenia." (PMID 24386483, 2013). "First, we did not perform analyses of other brain structural parameters such as specific white matter tracts that would provide further evidence of NRGN mediated connectivity disturbances in schizophrenia." (PMID 24386483, 2013). "We investigated the influence of NRGN rs12807809 on cortical thickness, subcortical volumes and shapes in patients with schizophrenia." (PMID 24386483, 2013). "The precise functions of NRGN and how it mediates cortical maturation and observed cortical thinning and thalamic shape abnormalities in schizophrenia are unclear at this juncture." (PMID 24386483, 2013). "miR-137’s regulation of NRGN may impact synaptic function and contribute to neurodevelopmental disorders like schizophrenia." (PMID 40779062, 2026). "Thus in this study, we aimed to study the influence of NRGN rs1280709 on cortical thickness and volumes and shapes of subcortical structures in patients with schizophrenia and in healthy subjects." (PMID 24386483, 2013). "The presence of cortical thinning alongside specific thalamic shape changes point towards the presence of thalamo-cortical morphological abnormalities in schizophrenia which may be partially mediated by NRGN." (PMID 24386483, 2013).
schizophrenia (continued). "Effects of NRGN genotype on GM volumes in patients with schizophrenia and in healthy controls." (PMID 22253779, 2012). "Reduced immunoreactivity of NRGN, which is expressed exclusively in the brain, has been observed in Brodmann areas (BA) 9 and 32 of the prefrontal cortex in postmortem brains from patients with schizophrenia compared with those in controls." (PMID 22253779, 2012). "Thus, the effects of NRGN genotype on GM volume of patients with schizophrenia and healthy controls were separately investigated." (PMID 22253779, 2012). "It targets genes and is essential for controlling synaptic plasticity, such as NRGN and CACNA1C, which are involved in neural development and synaptic function, contributing to the neurodevelopmental hypothesis of schizophrenia." (PMID 40779062, 2026). "RP11-677M14.2, a lncRNA located inside NRGN, while not previously identified through colocalization analysis, has been shown to be down-regulated in the amygdala of schizophrenia patients." (PMID 33046718, 2020). "NRGN, like DAOA, is involved in glutamate pathway regulation and may mediate effect of hypoglutamatergic function with impact on neural substrates in schizophrenia." (PMID 24386483, 2013).
cognitive decline (28 papers, 2017 to 2026). "CSF neurogranin was reported to be elevated in AD in association with increased t-tau and p-tau, and to be strongly related to cognitive decline." (PMID 38182581, 2024). "We found significant evidence to support an association between CX3CL1 and neurogranin, already in the early stages of cognitive decline." (PMID 37685973, 2023). "Cerebrospinal fluid (CSF) candidate markers (CHI3L1, parvalbumin) and synaptic proteins (SNAP-25, neurogranin, β-synuclein) may help identifying patients at higher risk of cognitive decline." (PMID 41960777, 2026). "β-Synuclein predicted MCI-to-dementia conversion and future cognitive decline and it performed better in discrimination of AD dementia patients than CSF neurogranin." (PMID 41673920, 2026). "Recent research has shown that CSF neurogranin levels are significantly elevated in AD patients compared to healthy individuals, correlating with cognitive decline and brain atrophy." (PMID 40002692, 2025). "Multiple studies have demonstrated that neurogranin measured in CSF and blood exosomes reflects synaptic dysfunction and correlates with cognitive decline." (PMID 40981206, 2025). "Neurogranin (NRGN) is a promising fluid biomarker for synaptic damage, showing both high CSF levels in AD and correlation with cognitive decline, as well as correlation with hippocampal volume and brain metabolic activity measured by FDG PET." (PMID 38350954, 2024). "The inclusion of neurogranin, a synaptic protein with AD specificity and predictive value for the future rate of cognitive decline, is a potential and promising addition to the AD CSF biomarker toolkit." (PMID 38920542, 2024). "Neurogranin (NRGN) is related to synaptic injury, moderate cognitive decline, traumatic brain injury, and cerebral ischemia." (PMID 36289630, 2022). "Neurogranin is a post synaptic protein involved in memory consolidation as well as a potential biomarker of cognitive decline and neurodegeneration in AD." (PMID 33986657, 2021). "In stratified analyses, weight loss was significantly associated with higher t-tau, p-tau, neurofilament light, and neurogranin, as well as faster cognitive decline in A+ participants only." (PMID 33597012, 2021). "Some of these targets, such as neurogranin, have been shown to have a good correlation with the rate of cognitive decline in patients with AD." (PMID 34497505, 2021). "The value of CSF neurogranin for the prediction of future cognitive decline was also identified, although the direction differed among studies." (PMID 32284537, 2020). "CSF neurogranin/Aβ1-42 ratios are also likely to help predict cognitive decline." (PMID 35448530, 2022). "Synaptic biomarkers such as neurogranin have been suggested to reflect cognitive decline." (PMID 29859129, 2018). "In addition, CSF neurogranin could be used to predict declines in memory and executive functions in the presence of mild cognitive decline." (PMID 35448530, 2022). "Furthermore, encouraging data show that increased neurogranin fragments in CSF correlate with future cognitive decline, brain atrophy, and glucose metabolism, even at early stages of the disease, and that the increase in CSF neurogranin seems to be specific for AD." (PMID 32122400, 2020). "Neurodegeneration-based markers in CSF, including NF-L, VILIP-1, neurogranin, and SNAP-25, also showed high positive correlations with neuronal damage in AD and MCI and can be used for evaluation and prediction of future cognitive decline in AD." (PMID 32806668, 2020).